COMT (catechol-O-methyltransferase)
Diseases named in the same sentence as COMT in open-access papers (continued):
Sharing a sentence is not in itself a finding about the gene and the disease.
depression (continued). "This study provides useful information on associations between anxiety/depression/chronic pain and OHRQoL/feelings of happiness/polymorphisms in the COMT, HTR2A, and FKBP5 genes in Brazilian adolescents, which are important, considering the limited research on this topic involving adolescents." (PMID 36834016, 2023). "On the other hand, in the present study, higher levels of depression were found to be associated with COMT Val158 allele homozygosity, extending previous evidence that an imbalance of dopaminergic transmission in psychosis is associated with a higher level of positive symptoms." (PMID 36833277, 2023). "Studies have investigated the association between anxiety and depression with polymorphisms in candidate genes involved in the neurotransmitter system and the stress response, such as Catechol-O-methyltransferase (COMT), Serotonin receptor 2A (HTR2A) and FK506-binding protein 51 (FKBP5)." (PMID 36834016, 2023). "So the higher enzymatic activity of the COMT Val158Met (substitution of methionine for valine at codon 158 encoded by a single nucleotide polymorphism) is associated with the greater degradation of dopamine and increased risk of depression and CVD." (PMID 35911274, 2022). "Hence, our results showed that the rs934945 of the PER2 circadian gene was significantly associated with depression scores, whereas anxiety level was associated with COMT rs4680." (PMID 34330229, 2021). "In addition, there are numerous genetic association studies implicating the COMT Val158Met polymorphism in major depression disorder." (PMID 34814943, 2021). "In a cross-sectional study of a large number of Chinese adolescents with depression, it was found that catechol-O-methyltransferase (COMT) gene VAL158MET polymorphism, DAT1 gene rs27072 polymorphism, and the peer relationship played an important role in adolescent depression symptoms." (PMID 34594253, 2021). "A randomized control trial (RCT) done in 2020 investigated whether neuroplasticity-associated SNPs like COMT gene and other gene variants affect the efficacy of transcranial direct current stimulation (tDCS) or escitalopram therapy in major depression." (PMID 34725583, 2021). "COMT has been implicated in both depression and cardiovascular disease (CVD)." (PMID 33273953, 2020). "Low COMT has been linked to anxiety and major depressive disorder." (PMID 31111659, 2019). "Catechol-O-methyltransferase (COMT) has previously been implicated in both depression and CVD." (PMID 30045690, 2018). "Additionally, this risk of CVD by high COMT activity genotype and depression was more pronounced in women compared to men." (PMID 30045690, 2018). "Thus, both an additive and a multiplicative interaction between depression and COMT Val158Met for risk of CVD were detected." (PMID 30045690, 2018). "Both additive interaction (attributable proportion (AP) = 0.56; 95% CI: 0.24-0.90 and synergy index (SI) = 4.39; 1.0-18.7) and multiplicative interaction (log likelihood test p = 0.1) was present between depression and COMT Val158Met in predicting risk of later CVD." (PMID 30045690, 2018). "We hypothesized that the relationship between depression, COMT polymoprphisms, especially rs4680, and pain susceptibility are complex and interrelated." (PMID 28740224, 2017). "Since pain syndromes as well as anxiety and depression are associated to low and high COMT activity respectively and these conditions are all associated with irritable bowel syndrome (IBS) we wanted for the first time to explore the relationship between the polymorphism and IBS." (PMID 21437260, 2011). "On the background that both chronic pain syndromes and anxiety/depression are associated to low and high COMT activity respectively and both are associated with IBS/IBS-like symptoms we wanted for the first time to explore the relationship between the val158met COMT polymorphism and IBS." (PMID 21437260, 2011).
depression (continued). "Low COMT activity has also been associated to chronic pain conditions such as facial pain, fibromyalgia and with non-migrainous headache, whereas the val/val genotype has been associated to anxiety/depression." (PMID 21437260, 2011). "Furthermore patients carrying a COMT val-allele tend to report more anxiety and more depression symptoms as compared to those with the met/met genotype." (PMID 21110842, 2010). "Our data suggest that the COMT 158val allele may be associated with more severe symptoms of general anxiety and possibly also depression in PD patients." (PMID 21110842, 2010). "We detected three polymorphisms (SLC6A4 intron 2 VNTR, 2 COMT polymorphisms) which may contribute to the genetic susceptibility to major depression, however, only one (SLC6A4) which held up to multiple comparison corrections." (PMID 16822313, 2006). "Studies in depression show that hypermethylation of COMT is associated with MDD, and often correlated with stress exposure and treatment response." (PMID 41234420, 2025). "However, stress seems to be a key factor in the etiology of major depressive disorder, and the COMT genotype could possibly enhance the predisposition to depression by altering the reactivity to stressors." (PMID 39202218, 2024). "5HT2A, TPH may be a risk gene for depression in women, and COMT may have a greater impact on men." (PMID 33193645, 2020). "Our study considered the interaction of COMT rs4680 and childhood emotional abuse, but previous studies investigated only the main effect of independent variables on each COMT polymorphism such as childhood trauma, current alcohol consumption, and related depression scores." (PMID 32618128, 2020). "Thus, together with the data showing that the COMT polymorphism predicted placebo responses in patients with irritable bowel syndrome and depression, these observations militate for a role of COMT in nocebo responses also for other physiological systems and diseases." (PMID 25222607, 2014). "In this context, variants in the monoamine-degrading enzymes, catechol-O-methyltransferase (COMT) and monoamine oxidase A (MAOA), modulate brain dopamine, norepinephrine, and serotonin levels and functions and have been linked to both depression and obesity." (PMID 41375608, 2025). "The psychiatric phenotypes affected by the COMT genotype exhibit sex-specificity, including smoking behavior, depression, and anxiety-related phenotypes where we observe a stronger association with the Val allele in women." (PMID 38540358, 2024). "The concurrent impact of depression (BDI score), sleep impairment (PSQI score), and the COMT Va158Met genotypes on the FM risk was evaluated by means of logistic regression." (PMID 38916531, 2024). "This overstimulation impairs COMT activity, which can result in chronic pain, anxiety, depression, and insomnia." (PMID 39350868, 2024). "Further studies should explore this SNP in FM patients in conjunction with COMT enzymatic activity and other symptoms connected with the dopaminergic system such as depression or sleep impairment." (PMID 38916531, 2024). "Other potential mechanisms include genetic factors (e.g., catechol-O-methyltransferase (COMT) and potassium inwardly rectifying channel subfamily J member 6 (KCNJ6) genes), lipid markers, and psychological risk factors (anxiety and depression)." (PMID 38731944, 2024). "The carriers of the rarest COMT rs4818-rs4680 haplotype (GA) had the highest scores on G1 item (somatic concern), while GG haplotype had the lowest scores on G2 (anxiety) and G6 (depression) items, compared to other haplotypes in male subjects." (PMID 37510262, 2023). "Moreover, a possible effect of events and genotypes on depression was explored, specifically, whether patients who had at least a major stressful event in the previous 6 months and were homozygous for the COMT Val158 allele or carrying the S allele of 5-HTTLPR showed the highest level of depression." (PMID 36833277, 2023).
depression (continued). "By considering the COMT genotype, patients who were Val158Val showed higher levels of depression when compared to those who were Val158Met or Met158Met (p = 0.029)." (PMID 36833277, 2023). "Genetic variants in both the serotonin transporter gene (SLC6A4, 5-HTT, or SERT) and in the catechol-O-methyltransferase (COMT) gene have been found to contribute to the pathophysiology of depressive disorder." (PMID 36833277, 2023). "COMT enzyme is involved with the breakdown of dopamine, estrogen, and other catecholamines, which have a role in the pathophysiology of depression." (PMID 35911274, 2022). "The expression of dopamine receptor D2 and transporter solute carrier family 6 member 3 (SLC6A3) in the penis was decreased, and the catechol-O-methyltransferase (COMT) was increased in the depression model rats." (PMID 36387873, 2022). "It has also been found that the interaction of polymorphisms of COMT rs4680 and s allele at 5-HTTLPR resulted in a gray matter volume change, which was associated with increased depression risk." (PMID 35207633, 2022). "In the context of G × E, COMT Val158Met has been found to interact with environmental variations to predict outcomes related to depression symptoms." (PMID 34814943, 2021). "That said, a clinical assessment of depression, by a clinician blind to dosage and COMT genotype, would provide additional strength to findings." (PMID 32459054, 2020). "Individuals carrying the Met/Met of COMT genotype are less likely to suffer depression than those carrying the Val/Val genotype." (PMID 33193645, 2020). "Those with depression and the high COMT enzyme activity genotype (Val/Val) had almost a three-fold increased risk of later CVD (OR 3.6; 95% CI: 2.0-6.6) compared to those non-depressed carrying the Val/Val allele." (PMID 30045690, 2018). "The risk for later CVD was increased in depressed persons with high activity COMT Val158Met genotype (Val/Val), with a synergistic interaction between depression status and COMT genotype." (PMID 30045690, 2018). "We concluded that depression and COMT rs4680 “GG” and “GA” genotypes and COMT rs6267 “GT” genotype contribute to pain in PD patients." (PMID 28740224, 2017). "Another study found an interaction effect between the COMT Val158Met genotype and recent stressful life events on depression onset." (PMID 27628896, 2017). "We next examined the distribution of genotypes and estimated odds ratio of the studied candidate SNPs of COMT, SNCA9A, and OPRM1 in relation to the risk of depression in our PD patients." (PMID 28740224, 2017). "fMRI research has explored the influence of the COMT genotype on both emotional processing and working memory in major depression." (PMID 29019461, 2017). "The effect of COMT rs4680 SNP in affecting pain severity was abolished in the subgroup of PD patients with depression." (PMID 28740224, 2017). "Although numerous studies have shown associations of COMT with PTSD and depression, the mechanisms underlying this gene–disease association are not clear." (PMID 27683563, 2016). "When controlling for depression and anxiety scores, the differences for the COMT SNP rs174697 on the cortical thickness for the left postcentral gyrus remained significant." (PMID 26288143, 2015). "A group of pharmaco-genetics studies showed that COMT variations are correlated with the effective management of depression." (PMID 24505324, 2014). "In fact, the application of COMT inhibitors in depression treatment was approved for a US patent in 2005 (US 20050137162 A1)." (PMID 24505324, 2014). "To conclude, in this study we aimed to study the relationship between COMT function and IBS, both of which have been demonstrated to be associated with pain and anxiety/depression." (PMID 21437260, 2011). "Patients with the COMT met/met genotype had a lower incidence of comorbidity with depression as compared to val-carriers." (PMID 21110842, 2010).
depression (continued). "The 5-HTT and COMT genes have been subjects of interest in the context of depression and anxiety." (PMID 39590895, 2024). "In the COMT group, there was a significant difference through the four stress conditions (Wilks’ λ; p < 0.015), and there was especially a main effect on the “Depression” scale (Mauchly’s W; F = 4.475, p < 0.001)." (PMID 39590895, 2024). "The specific indications for prescribing certain treatments are also unclear, such as pramipexole, which can be effective for both depression and motor problems, and catechol-O-methyltransferase (COMT) inhibitors, which has an impact on both motor symptoms and abdominal discomfort." (PMID 38217612, 2024). "Associations may also exist between environmental substance exposure and genetic factors (e.g., catechol-O-methyltransferase (COMT) polymorphism) in the development of hearing loss, neurobehavioral disorders, and depression." (PMID 39330578, 2024). "There was a main effect only on the “Depression” scale in COMT (Mauchly’s W; F = 2.643, p < 0.026)." (PMID 39590895, 2024). "Our hypothesis is that OHRQoL, feelings of happiness, and polymorphisms in candidate genes, such as COMT, HTR2A and FKBP5, could be associated with anxiety, depression and chronic pain." (PMID 36834016, 2023). "Male carriers of COMT rs4818–rs4680 GA haplotype had the highest scores on the G1 item (somatic concern), whereas GG haplotype carriers had the lowest scores on G2 (anxiety) and G6 (depression) items." (PMID 37510262, 2023). "It has been found that higher levels of depression is associated with the presence of SLEs (p = 0.019) and with COMT Val158 allele homozygosity (p = 0.029), but not with carrying the S allele of 5-HTTLPR." (PMID 36833277, 2023). "COMT has been associated with elevated proportions of tension/restlessness, anxiety, and depression in individuals not diagnosed with ASD." (PMID 37895967, 2023). "The novelty of the results of the present study concerns the genetic background, finding an association between depression and the COMT gene but not with the 5-HTTLPR gene." (PMID 36833277, 2023). "Catechol-O-methyltransferase (COMT) is closely related to depression." (PMID 35888708, 2022). "Although SLC6A3 (DAT1) and COMT genes were significant for the risk of suicidal attempts, they showed a lack of association with the severity of the symptoms of depression, situational anxiety, and personal anxiety." (PMID 34199792, 2021). "Genetic variations of COMT Val158Met may be a critical candidate in understanding the development of depression and NSSI." (PMID 34814943, 2021). "Moreover, our study found that the COMT Val158Met polymorphism moderates the link between harsh parenting and NSSI and the link between harsh parenting and depression in the mediation model of the relationship between harsh parenting and NSSI." (PMID 34814943, 2021). "In this study, we examined whether MDD patients with Met/Met, Met/Val, and Val/Val COMT genotypes differed in their response to bupropion in terms of depression scores." (PMID 32459054, 2020). "However, sexual dimorphism of COMT gene has been also reported in various neuropsychiatric disorders such as anxiety disorders, depression, attention deficit hyperactivity disorder, and obsessive-compulsive disorder." (PMID 30018555, 2018). "The purpose of this study was to assess if COMT Val158Met, which influences the COMT enzyme activity, has an effect on the risk of cardiovascular disease (CVD) in individuals with a history of depression and also to determine if the risk differs depending on gender." (PMID 30045690, 2018). "Accordingly, we found that high activity COMT (Val/Val)*depression was associated with increased CVD risk in women, but not in men." (PMID 30045690, 2018).
depression (continued). "Using a large population-based Swedish cohort of adults we here show for the first time that the COMT Val158Met genotype, corresponding to high COMT enzymatic activity, implies an increased risk of CVD especially for those who had depression up to 14 years earlier." (PMID 30045690, 2018). "After stratified by depression status, the association between COMT rs6267 GT genotype and the intensity of pain perception still remained significant in PD patients without depression (23.32 ± 5.9 vs. 4.68 ± 10.2, P < 0.01)." (PMID 28740224, 2017). "After stratified by depression status, the association between COMT rs6267 GT genotype still remained significant in PD patients without depression." (PMID 28740224, 2017). "The association of COMT Val158Met to ToM decoding accuracy did not even approach significance, either as a main effect or in interaction with depression group." (PMID 26974654, 2016). "Further, specificity tests of genetic associations could be extended by accounting for other candidate genes implicated in depression risk (e.g., HOMER1, TPH, DRD4, COMT)." (PMID 24312122, 2013). "The Met/Met homeostatic response to sleep loss may possibly relate to several recent reports of differential responses to treatment in depression as a function of the COMT Val158Met genotype." (PMID 22216231, 2011). "Additionally, it has been suggested that the effects of the COMT genotype on antidepressant responses may depend on other factors, such as the type of medication, severity and duration of depression, and other genetic and environmental factors." (PMID 37239455, 2023). "Additionally, and in accordance with the influence of depression on the NFR response, FM patients with lower NFR thresholds were more likely to possess the Met/Met genotype of the COMT Val158Met polymorphism (this was less common among individuals with depression)." (PMID 35579545, 2022). "Our study demonstrated a strong relationship between depression scores and cognitive impairment, sleep quality, marital status, fosaprepitant intake, and PER2 polymorphism, while anxiety scores were correlated to cognitive impairment, insomnia severity, fosaprepitant intake, and COMT polymorphism." (PMID 34330229, 2021). "•Association between COMT haplotype and depression over life course has not explored." (PMID 29331705, 2018). "The influence of depression on the Val/Val-CVD association may in part be through increased inflammation and oxidative stress often seen in the depressed state, which could potentiate a high COMT enzyme activity effect on cardiovascular function." (PMID 30045690, 2018). "Furthermore, COMT haplotypes did not play a major role in the susceptibility of either pain or depression in our study population." (PMID 28740224, 2017). "Moreover, the COMT rs6267 “T” allele is significantly correlated with KPPS scores after the effects of onset age, disease duration, and severities of motor symptoms and depression are considered." (PMID 28740224, 2017). "Both childhood trauma and a functional catechol-O-methyltransferase (COMT) genetic polymorphism have been associated with posttraumatic stress disorder (PTSD) and depression; however, it is still unclear whether the two interact and how this interaction relates to long-term risk or resilience." (PMID 27683563, 2016). "There may be complex relation among PD, depression, and COMT gene." (PMID 24825955, 2014). "All of the available evidence indicates that COMT inhibitors may have an effect on depression." (PMID 24505324, 2014). "CVD, cardiovascular disease; COMT, catechol-O-methyltransferase; KNHANES, Korea National Health and Nutrition Examination Survey; MSD, moderate to severe depression; DII, dietary inflammatory index." (PMID 35911274, 2022).